CXCL10 (C-X-C motif chemokine ligand 10)
Diseases named in the same sentence as CXCL10 in open-access papers (continued):
Sharing a sentence is not in itself a finding about the gene and the disease.
melanoma (continued). "Finally, a recent study demonstrated that LPS-activated melanoma-resident MCs can secrete CXCL10, which, in turn, recruits tumor-infiltrating effector T cells (TILs) and initiates melanoma immune defense." (PMID 35159157, 2022). "Moreover, our data revealed that the SASP of cytokine-treated melanoma cells contains high amounts of anti-angiogenic chemokines such as CXCL10 or CXCL11, thereby pointing to an acute, anti-tumoral effect of CIS that has already been described." (PMID 35563820, 2022). "In addition, high expression of CXCL10 in patients suffering melanoma is an indicator of a good prognosis." (PMID 35145233, 2022). "PD-1 blockade increased tumor expression of CXCL10 in melanoma-bearing mice treated with ACT." (PMID 33603130, 2022). "Functional studies in the CXCL10 reporter vitiligo model mice and single-cell RNA sequence of the human vitiligo skin revealed that antigen-presenting cells, including DCs and macrophages, upregulated CXCL10 to the greatest extent on a per-cell basis, which was similar to melanoma." (PMID 35432377, 2022). "Given that an inversed relation between the tumor weight and CD8+ T cell infiltration and a dramatic downregulation of Cxcl10 in melanoma at the late stage, we tested if addition of IFNα or IFNα-MSCs could enhance the expression of CXCL10 in B16F0 cells." (PMID 35145233, 2022). "It has been reported that ligation with CXCL10 increased the metastasis of melanoma." (PMID 35145233, 2022). "Indeed, both pre- and post-treatment CXCL9 and CXCL10 expression levels correlate with response to anti-PD-1 treatment in melanoma patients and anti-PD-L1 treatment in urothelial cancer patients." (PMID 34030676, 2021). "Four of these Top HRLs are recognized by 2 of the Top HRs and represent ligand-receptor pairs that have been previously identified as crucial mediators of T and B cell trafficking in melanoma: CXCL10 and CXCL9 are ligands for CXCR3; and CCL4 and CCL5 are ligands for CCR5." (PMID 34454518, 2021). "In addition, a significant increase in serum CXCL10 and Kyn/Trp was observed after 1 cycle of anti-PD-1 in the melanoma cohort." (PMID 34071888, 2021). "Thus, the association of PRAME, CXCL9, CXCL10, S100A7, S100A8, and S100A9 with melanoma progression is supported by prior studies and commercially available clinical tests." (PMID 35008167, 2021). "CXCL10 is considered a potential therapeutic target for melanoma." (PMID 34439306, 2021). "No clear immune boost effect could be observed after SBRT in these 2 small patient cohorts except from a moderate increase in CXCL10 in the melanoma cohort." (PMID 34071888, 2021). "In addition, CD26 inhibition was reported to enhance T lymphocyte trafficking into melanoma tumor by inducing the intra-tumor expression of CXCL10, further improving the efficacy of immunotherapy." (PMID 32582551, 2020). "Furthermore, IFN-γ treatment induced chemokines CXCL9 and CXCL10 in melanoma potentially facilitating T cell infiltration." (PMID 30899263, 2019). "Moreover, higher serum levels of the chemokine CXCL10 are present in melanoma patients developing leukoderma after immunotherapy compared with vitiligo patients or healthy controls." (PMID 31731645, 2019). "In addition, patients with ESCC showing higher CXCL10 expression had a better overall survival rate when compared with CXCL10-negative patients, while enhanced proliferation and metastatic behavior of melanoma tumor cells could be linked to higher CXCL10 secretion." (PMID 31216755, 2019). "In addition, other reports also suggested that serum CXCL10 levels were correlated with disease activity in advanced melanomas and angiosarcomas." (PMID 31080803, 2019). "Moreover, therapies such as dacarbazine and temozolomide induce the CD8+ T cell chemoattractants CCL5, CXCL9, and CXCL10 in human melanoma cell lines." (PMID 30899263, 2019). "Additionally, oxaliplatin has been shown to induce CXCL10 secretion by melanoma cells, another ICD feature." (PMID 31861811, 2019).
melanoma (continued). "Finally, cisplatin was shown to induce CRT expression in B16 melanoma cells and CXCL10 expression in vivo." (PMID 31861811, 2019). "Similarly, we found that activated CXCR3 positive human NK cells selectively migrated towards CXCL10 positive human melanoma tumors in an in vivo xenograft model." (PMID 31340613, 2019). "In xenograft mice models, these expanded NK cells could be efficiently recruited toward CXCL10+ melanomas." (PMID 30319622, 2018). "However, the treatment with CXCL10 significantly reduced the in vitro invasiveness of melanoma, as well as reduced the melanoma tumor growth and metastasis in C57BL/6 mice." (PMID 30686982, 2018). "Similarly, murine-leukemia virus (MLV)-derived replication-competent retroviruses were used to stably express CXCL10 in fibrosarcoma, melanoma and Lewis lung cancer models and were shown to inhibit tumor growth in vivo." (PMID 30319622, 2018). "However, in human melanoma, the angiostatic effects of CXCL10 are mediated through CXCR3, in a GAG-independent manner." (PMID 29379506, 2017). "Interestingly, elsewhere an anti-angiogenic and anti-melanoma effect has been reported to be related to a pro-inflammatory state mediated by pro-inflammatory cytokines such as CXCL10/IP-10." (PMID 27764787, 2016). "In melanoma, it has been demonstrated that up regulation of expression of several chemokine genes such as Ccl2, Ccl3, Ccl4, Ccl5, Cxcl9, and Cxcl10 in the tumor microenvironment correlates with the recruitment of activated effector T cells to the tumor increasing antitumor immunity." (PMID 27876058, 2016). "The protective role of CXCL10/IP-10 has been already investigated in melanoma." (PMID 27764787, 2016). "We then conclude that the activation of pro-inflammatory pathways may underlie, at least to a certain extent, the anti-angiogenic and anti-melanoma effect of PDGFR-alpha via CXCL10/IP-10." (PMID 27764787, 2016). "The current study is the first indicating that the anti-melanoma role of PDGFR-alpha may be linked to the known anti-melanoma role of CXCL10/IP-10, and suggests PDGFR-alpha and CXCL10/IP-10 as related targets in melanoma therapy, likely via miR-503." (PMID 27764787, 2016). "CXCL10 was the only chemokine secreted in the studied melanoma cell lines." (PMID 24559071, 2014). "From all the chemokines studied, the only chemokine secreted by the melanoma cell lines was CXCL10." (PMID 24559071, 2014). "Finally, ADAR1i-124, like siAdar1, upregulated expression of IFN-stimulated genes (ISGs) such as Ifih1 (MDA5), Cxcl9, and Cxcl10 in Yumm1.7 melanoma and HGS2 ovarian cancer (OC) cells, indicating that ADAR1i-124 activates IFN signaling, a crucial step for effective ICB." (PMID 41608661, 2026). "In mouse malignant melanoma cell lines B16F10 and Yummer1.7, knockdown of USP35 by shRNAs, which specifically targeted USP35 mRNA, significantly enhanced VSV virus-induced expression of inflammation and antiviral-associated factors, including IFNβ, CXCL10, and ISG15." (PMID 40016186, 2025). "Moreover, DNA-methylation inhibition increased CXCL9/CXCL10 secretion, overexpression of major histocompatibility complex class I/II antigens and components of the antigen-processing machinery, thus suggesting the augmentation of melanoma immunogenicity." (PMID 39867570, 2025). "In addition, not only immune cells but also melanoma cells are able to produce CXCL10." (PMID 38928238, 2024). "Furthermore, overexpression of CXCL10 inhibits tumor growth in melanoma and sarcoma." (PMID 37484915, 2023). "In addition, CXCR3, the receptor for CXCL10, is upregulated in brain-tropic melanoma cells." (PMID 33466236, 2021). "Indeed, a demethylase, 5AZADC, treated melanoma cells following dsDNA stimulation and showed recovered IFN-β and CXCL10 production in melanoma cells suggesting that DNA methylation might play a role in the regulation of STING in melanoma." (PMID 34830754, 2021).
melanoma (continued). "Interestingly, immunokine profiling studies in the cerebrospinal fluid (CSF) of advanced melanoma patients showed that elevated levels of CXCL10, CCL17, and CCL4 may correlate with a more aggressive development of brain metastases." (PMID 33466236, 2021). "Of major relevance, spontaneous regression of melanoma and other melanocytic lesions were associated with activation of endogenous type I interferons and infiltration by plasmacytoid dendritic cells and CXCR3+ cytotoxic T cells, these last recruited by elevation of CXCL10." (PMID 29064427, 2017). "Intratumoral injection of CXCL10 leads to reduced growth and impaired angiogenesis and metastasis in murine adenocarcinoma and studies have shown a synergistic effect against tumours through its immunomodulatory properties in murine models of glioma and melanoma." (PMID 24395654, 2014). "Specifically, pro-inflammatory CXCL9+CXCL10+ TAMs are enriched in SCC, while tissue-remodelling SPP1+ TAMs are predominant in melanoma." (PMID 41636115, 2026). "In melanoma cells, IFN‐γ signalling has been demonstrated to drive antigen presentation and the release of chemokines that recruit T cells (such as CXCL9 and CXCL10)." (PMID 39812592, 2025). "Intratumoural expression of anti-tumoural chemokines such as CXCL9, CXCL10 and CCL5 were reported in patients undergoing chemotherapy for multiple cancer types such as melanoma, non-small cell lung cancer (NSCLC) and BC." (PMID 40852716, 2025). "Thus, our results support a model in which IκBζ-mediated recruitment of EZH2 and HDAC3 represses Cxcl10, Cxcl9, and Ccl5 in melanoma, contributing to the observed lack of T-cell infiltration and immunotherapy resistance in the α-PD-1-treated, IκBζ-expressing melanoma mouse models." (PMID 40562773, 2025). "In this respect, antagonists of the Toll-like receptors TLR2 and TLR6 synergistically with IFN-γ increase the expression of C-X-C motif chemokine ligand 10 (CXCL10), CXCL11, IL-8, IL-32, and cathepsin S in melanoma cells." (PMID 40108693, 2025). "Based on these findings, we propose that constitutively expressed IκBζ in melanoma recruits HDAC3 and EZH2 to the gene loci of CXCL9, CXCL10, and CCL5, leading to inaccessible promoter regions of these genes." (PMID 40562773, 2025). "Concurrently, suppression of IFN-γ response genes (CXCL9, CXCL10, STAT1) mirrors observations in melanoma and lung cancer, where similar transcriptional silencing correlates with T cell exclusion and ICI resistance." (PMID 40873541, 2025). "We previously demonstrated that B16-F10 melanoma cells, which are resistant to anti-PD-1 therapy in vivo, exhibit relatively low expression of CCL5 and CXCL10, two key chemokines essential for recruiting NK and CD8+ T cells to the tumor microenvironment." (PMID 40248897, 2025). "The macrophage-centric gene signature described in this study, comprising CLEC4A, CXCL10, and LAT2, furnishes robust evidence that macrophages can vary widely in their functional states within melanoma lesions." (PMID 40607411, 2025). "The C-X-C motif chemokine ligand genes CXCL9, CXCL10, and CXCL11 were up-regulated in patients with high MOTIscores in gastric cancer and melanoma, and we confirmed this finding for different cancer types in the independent MTB cohort." (PMID 41463470, 2025). "Cytokine profiling of SPOP-depleted human melanoma A2058 cells revealed increased expression of interferon-stimulated genes (ISGs), including IFIT1, CXCL10, and MX1, which was validated by RT-PCR." (PMID 41148213, 2025). "CD8+ T cells from melanoma tumour mass of LSP1 KO mice exhibited higher migration ability in response to CXCL9 and CXCL10, whereas T cell-specific LSP1 overexpression in transgenic mice resulted in suppressed immune infiltration and promoted melanoma growth." (PMID 40038352, 2025). "In BRAF- and NRAS-mutant melanoma patients, low ACKR2 expression or high CCL5/CXCL10 levels correlated with improved survival and higher CD8+ T cell markers." (PMID 40248897, 2025).
melanoma (continued). "Recent studies on anti-PD1 monotherapy have demonstrated that CXCL9 and CXCL10 were crucial, since its receptor CXCR3 was found to be the arbitrator for the PD-1+ CD8+ T cells infiltration in B16 murine melanoma tumours." (PMID 40852716, 2025). "Using Pf4 Cx3cr1 mice to deplete CD206hi IMs expressing Cxcl13, Cxcl9, and Cxcl10, we demonstrate their essential role in TLS formation, lymphocyte recruitment, and tumor suppression in melanoma and lung adenocarcinoma." (PMID 40630529, 2025). "In fact, in melanoma models, as the VPS34 kinase inhibitors SB02024 or SAR405 induced a rise in CCL5, CXCL10 and IFN‐γ in the TME along with an increase in the extent of NK and T‐cell infiltration, the inhibition of melanoma was greatly enhanced." (PMID 38652105, 2024). "Administration of CXCL10-Fc and CXCL9-Fc limits melanoma growth while selecting subtypes of effector and cytotoxic CD4+ and CD8+ T cells with an IFN-γhigh signature, further limiting tumor growth." (PMID 39474427, 2024). "Four region-specific marker genes (PMEL for melanoma region, COL1A1 for stroma region, CXCL10 for lymphoid tissue 2, and MS4A1 for lymphoid tissue 1) were identified from the ST data to demonstrate the accuracy of imputed expression." (PMID 39402626, 2024). "However, the role of endogenous CXCL10 from the host in melanoma tumor growth remains unclear." (PMID 39268223, 2024). "Several studies have found a strong correlation between the expression of CCL5 and CXCL10 in tumors and the infiltration of CD8+ T lymphocytes in different types of cancer, such as colorectal cancer, melanoma, and esophageal squamous cell carcinoma." (PMID 38448406, 2024). "Specifically, melanoma patients treated with immunotherapy have been shown to have better survival rates when the tumor expresses CXCL9 and/or CXCL10." (PMID 38396726, 2024). "In numerous cancers, among them melanoma, non-small cell lung cancer (NSCLC), ovarian cancer, gastric cancer, and colorectal cancer, high CXCL9/CXCL10 levels indicate favorable prognosis, and low levels indicate poor prognosis." (PMID 39474427, 2024). "Upregulations of Cxcl9, Cxcl10, Cxcl11, Ccl5, Tap1, CD74, Irf1, Icam1, CD40, Fas and PD-L1 were detected after Mi-2β silencing and the anti-PD-1 treatment in BRafV600E/Ptennull melanomas." (PMID 38461299, 2024). "Hydrogel‐generated gradients of murine CXCL10, conjugated to intratumorally injected hydrogel solutions via PolyG‐azidoesters, elicited the recruitment of CD8+ T‐cells in a “cold” syngeneic melanoma model." (PMID 39553428, 2024). "We found that CXCL10 activated signaling pathways involved in pro-angiogenic factor expression and tumor growth in B16F10 melanoma cells." (PMID 39268223, 2024). "The most relevant human cancers in this context are melanoma, non-small cell lung cancer (NSCLC), ovarian cancer, gastric cancer, and colorectal cancer, where high levels of CXCL9/CXCL10 indicate favorable prognosis and low levels poor prognosis." (PMID 39474427, 2024). "Therefore, CXCL10 might represent a therapeutic target for melanoma." (PMID 39268223, 2024). "The heatmap displayed that melanomas with high IRE1α activity have increased expressions of TIL signature molecules like IFNG, GZMB, CD8A and CXCL10." (PMID 38291473, 2024). "The ITRGM signature includes GBP5, HLA-DPB1, XBP1, CD40, CXCL10, and TNFSF13B, each playing pivotal roles in the immune response and tumor microenvironment of melanoma." (PMID 39355255, 2024). "Taken together, these results indicate that CXCL10 can activate signal pathways involved in pro-angiogenic and pro-growth in B16F10 melanoma cells and CXCL10 can directly enhance B16F10 tumor growth in an in vitro 3D cell culture system." (PMID 39268223, 2024). "Expanding upon these clinical observations, we have demonstrated that melanoma patients with elevated cGAS levels also exhibit increased expression of CCL5 and CXCL10, as illustrated in." (PMID 38506049, 2024).
melanoma (continued). "IP-10 (CXCL10), for example, demonstrated immunomodulatory potential to recruit APCs in glioma and melanoma murine tumor models." (PMID 38504975, 2024). "In addition, our study allows the identification of an immunosuppressive signature characterized by high GLI and low cytokine/chemokine expression (CCL7, CCL2, CCL20, CXCL8, CXCL1 and CXCL10), which could be used to stratify melanoma patients with poor survival." (PMID 39090759, 2024). "Taken together, we conclude that MC1R represses the expression of Cxcl9, Cxcl10, and Cxcl11 in B16F10 melanoma." (PMID 37714844, 2023). "Our previous cytokine and chemokine profiling in short term cultures of dissociated YUMM3.3 melanoma grafts showed that Activin-A secretion by the cancer cells diminishes both the levels of IFN-γ and the secretion of CXCL9 and CXCL10 in the conditioned medium." (PMID 38304252, 2023). "Other studies on cisplatin and DTX have shown that the expression of Cisplatin-induced CXCL10 and DTX–induced CXCL11 by melanoma cells affects lymphocyte recruitment and infiltration within tumors." (PMID 38057843, 2023). "In an exploratory fashion, we further studied melanomas from 5 patients with coordinately elevated serum levels of TNFSF13 and CXCL10 or CXCL13." (PMID 37435077, 2023). "First, activating toll‐like receptors and ribonucleic acid helicases from melanoma cells stimulates the secretion of IFN‐a/β from histiocytes and endothelial cells, which secrete CXCL10." (PMID 37170733, 2023). "Other chemokine ligands important during the metastatic process include the CXCR3 ligand CXCL10 (in melanoma and colorectal cancer), the CXCR4 ligand CXCL12 (in multiple types of cancer) and CCL1 (in melanoma)." (PMID 37744339, 2023). "CXCL10 and STAT1 have also been suggested as key candidate genes for understanding the molecular mechanism of melanoma." (PMID 37048082, 2023). "Based on a set of microscopic, functional and in silico analyses, we demonstrated that the melanoma milieu directly impairs IFN-α and CXCL10 production by pDCs via TLR-7/9 and cGAS-STING signaling pathways." (PMID 38239354, 2023). "CXCL10 is a powerful angiogenesis inhibitor that binds to CXCR3 receptors and suppresses melanoma’s angiogenesis by decreasing intra-tumor vascular density and boosting apoptosis and necrosis of malignant tissue." (PMID 35982458, 2022). "determined that CXCL10/CXCR3 coexpression increased tumor cell metastasis and recurrence in both in vitro and in vivo analyses of B16F1 melanoma." (PMID 35702353, 2022). "A six-gene IFN-γ signature (including IDO1, CXCL10, CXCL9, HLA-DRA, STAT1, and IFNG) was identified in a melanoma cohort of the KEYNOTE-001 study to predict response to pembrolizumab." (PMID 35222540, 2022). "In a melanoma model, TLR2/6 agonists + IFN-γ can induce CXCL10 production, leading to more T cells migrating into TME." (PMID 35818037, 2022). "In contrast, attenuating PRMT5 activity by short hairpin RNA or the small molecular inhibitor, EPZ015666 in melanoma B16 cells, increased CCL5 and CXCL10 expression after stimulation." (PMID 35493527, 2022). "The subcutaneous injection of lethal or sub-lethal doses of melanoma B16 cells into CXCR3-/-mice establish a critical role for CXCR3 as a receptor for CXCL9, CXCL10, and CXCL11 during CTL migration." (PMID 35493527, 2022). "Radiation therapy in melanoma-bearing mice induced Type I IFN and CXCL10 production by myeloid cells because cytosolic dsDNA released from dying cancer cells activates the STING pathway in dendritic cells." (PMID 35626062, 2022). "For example, oxaliplatin induces the CXCL10 production by melanoma cells and cisplatin triggers the CXCL10 (together with CRT) expression in vivo in a B16 melanoma model." (PMID 36429101, 2022). "For other chemokines, most of them tended to express higher in FGFR Mut melanoma, such as CCL5, CCL19, CXCL9, CXCL10, CXCL11, CXCL13 and CXCL14 (all P > 0.05)." (PMID 36426352, 2022).